MTOR (mechanistic target of rapamycin kinase)
Diseases named in the same sentence as MTOR in open-access papers (continued):
Sharing a sentence is not in itself a finding about the gene and the disease.
anemia (continued). "In clinical allotransplantation, the long-term efficacy of rapamycin and other mTOR inhibitors has been firmly established, despite the fact that adverse events have been reported, such as the inhibition of wound healing, buccal ulceration, anemia, hyperglycemia, dyslipidemia, and thrombocytopenia." (PMID 37759601, 2023). "Combination therapy with CDK4/6 and mTOR inhibitors could also enable the use of lower doses, thus diminishing adverse effects and toxicity in patients, as neutropenia, leukopenia, thrombocytopenia, anemia, fatigue or diarrhea." (PMID 36792625, 2023). "The introduction of mTOR inhibitors, particularly everolimus, provides a promising alternative in managing PVB19-related anemia." (PMID 38775967, 2024). "The most frequently reported grade ≥ 3 TEAEs included anemia, neutropenia, fatigue, and hypophosphatemia, which is consistent with the known safety profiles, and as expected for inhibition of the PI3K/AKT/mTOR pathway." (PMID 37839313, 2023). "These include anemia, expanded criteria donors (ECD), delayed graft function (DGF), prolonged ischemia time, the presence of urological complications, and the use of steroids or mTOR inhibitors." (PMID 40943861, 2025). "On the other hand, immunosuppressants (e.g. calcineurin inhibitors vs. mTOR-inhibitors) did not seem to affect the prevalence of anemia." (PMID 34078389, 2021). "The development of left ventricular hypertrophy (LVH) involves classic factors suchas anemia, changes in renin-angiotensin-aldosterone system (RAAS), and hypertensionin addition to the independent mechanisms from the mTOR, phosphorus, and parathyroidhormone (PTH)." (PMID 29738042, 2018). "We inferred that increased mTOR in NRBC might suppress autophagy, facilitate abnormal mitochondrial accumulation, and finally lead to anemia in MDS." (PMID 29967662, 2018).
ischemic stroke (59 papers, 2013 to 2025). A stroke disorder caused by obstruction of blood flow to the brain, due to thrombotic (local blood clot formation) or embolic (due to a blood clot or other material traveling from another site) event. "Autophagy is a biological process that degrades and removes cellular materials via the lysosomal pathway, while the pathological damage in ischemic stroke is partly caused by autophagy dysfunction via the mTOR-dependent pathway." (PMID 36903613, 2023). "The purpose of this review is to examine the current literature and propose potential underlying mechanisms involving Kir4.1, specially the mammalian target of rapamycin (mTOR) and/or autophagic pathways, in the pathogenesis of ischemic stroke." (PMID 29503609, 2018). "The findings suggest that age-dependent dysregulation of the Akt/mTOR and Akt/FOXO3a signaling pathways, in combination with impaired energy metabolism, underlies the observed differences in the severity and outcomes of ischemic stroke." (PMID 41515961, 2025). "We found that elevated microvascular endothelial P-gp degraded endothelial tight junction, increased BBB hyperpermeability, accelerated brain inflammation and thus worsened ischemic stroke outcomes in association with increased Akt/mTOR activity and reduced endothelial autophagy." (PMID 36186136, 2022). "Several studies have indicated AMPK/mTOR signaling was related with autophagy and played a critical role in ischemic stroke." (PMID 40581646, 2025). "GRB2 plays a key role in neuroprotection, reducing neuronal damage through the regulation of autophagy and the Akt/mTOR pathway in ischemic stroke." (PMID 40299522, 2025). "Recent research indicates that inhibiting PI3K/Akt/mTOR signaling exacerbates neuronal apoptosis and autophagy in ischemic stroke." (PMID 41011203, 2025). "Quantitative Reverse Transcription Polymerase Chain Reaction (qRT-PCR) analysis showed that in young patients, ischemic stroke was accompanied by coordinated activation of both the pro-survival PI3K/Akt/mTOR cascade and the stress-induced PI3K/Akt/FOXO3a axis." (PMID 41515961, 2025). "Hou, etc. ’s study showed that mTOR phosphorylation was reduced, along with Bcl-2 expression in the animal model of ischemic stroke." (PMID 38015410, 2024). "In this context, mTOR emerges as a compelling candidate for inclusion in intervention strategies aimed at ameliorating ischemic stroke pathology." (PMID 38666949, 2024). "As with the case of neurons, autophagy regulation in glial cells following ischemic stroke also involves the mammalian target of rapamycin (mTOR) pathway and AMP-activated protein kinase (AMPK)." (PMID 37987924, 2024). "In conclusion, our review underscores the critical roles of the RhoA/ROCK and mTOR signaling pathways in ischemic stroke pathophysiology, alongside the emerging potential of secretome-based therapies." (PMID 38666949, 2024). "Currently, diverse perspectives exist regarding the impact of ischemic stroke on the AKT/mTOR signaling pathway." (PMID 39639187, 2024). "Studies have demonstrated the dual role of mTOR in ischemic stroke pathophysiology, with both neuroprotective and neurotoxic effects observed depending on the context and timing of its activation." (PMID 38666949, 2024). "This study confirmed that Nek6 regulates autophagy and alleviates CIRI through the mTOR signaling pathway, which provides a novel therapeutic strategy for patients with ischemic stroke in the future." (PMID 39702325, 2024). "Targeting mTOR signaling for ischemic stroke treatment poses therapeutic challenges due to its intricate regulatory network and pleiotropic effects." (PMID 38666949, 2024). "In the context of ischemic stroke, dysregulation of mTOR signaling contributes to neuronal injury, neuroinflammation, and impaired tissue repair." (PMID 38666949, 2024). "Cellular autophagy is known to be regulated by multiple signaling pathways, among which the Akt/mTOR pathway is crucial in autophagy regulation during ischemic stroke." (PMID 36903613, 2023).
ischemic stroke (continued). "The activation of the Akt/mTOR pathway was reported to play important roles in both autophagy regulation and ischemic stroke progression." (PMID 36903613, 2023). "Collectively, these results showed that Nampt released by OGD/R-ADEXs ameliorated acute ischemic stroke during neuronal injury by targeting AMPK/mTOR signaling to induce autophagy." (PMID 36539418, 2022). "Several studies have indicated that AMPK/mTOR signaling was related with autophagy, and played a critical role in ischemic stroke." (PMID 36539418, 2022). "We confirmed that HQ-HH can treat ischemic stroke through the PI3K-Akt-mTOR autophagy pathway and showed that HQ-HH can promote the recovery of intestinal flora in rats after ischemic stroke." (PMID 35111232, 2022). "According to another study, mTOR signal pathway achieved a vital function for protection against ischemic stroke." (PMID 35095491, 2021). "According to these results, we can conclude that EA treatment exerted neuroprotective effects by regulating the PI3K/AKT/mTOR pathway after ischemic stroke." (PMID 32477073, 2020). "We have reported that conventional protein kinase Cγ (cPKCγ)-modulated neuron-specific autophagy improved the neurological outcome of mice following ischemic stroke through the Akt-mechanistic target of rapamycin (mTOR) pathway." (PMID 29734780, 2018). "In this study, we investigated the effects of CD4 T cell deficits on oxidative stress and on the Akt/mTOR cell signaling pathways after ischemic stroke in mice." (PMID 32832192, 2018). "Some research suggested that regulating the activity of mTOR should be developed as a potential therapeutic strategy for ischemic stroke." (PMID 27465579, 2016). "The current study investigates the effects of rapamycin on mTOR signaling and neuron survival in an in vitro model of ischemic stroke using oxygen glucose deprivation (OGD)." (PMID 23861877, 2013). "Considering that under normal physiological conditions Akt suppresses FOXO proteins, ischemic stroke may result in insufficient Akt (and consequently mTOR) activity, leading to uncontrolled FOXO3a activation." (PMID 41515961, 2025). "Additionally, flavonoids such as baicalein have demonstrated neuroprotective effects in ischemic stroke models by activating the PI3K/Akt/mTOR pathway, thereby inhibiting excessive autophagy and reducing neuronal apoptosis." (PMID 41007413, 2025). "Therefore, lncRNA AC136007.2 improves ischemic stroke through the suppression of autophagy in an AMPK/mTOR-dependent manner." (PMID 39021183, 2024). "It is worth exploring whether lithium can modulate autophagy through mTOR to inhibit ferroptosis in ischemic stroke models." (PMID 38169754, 2024). "It is noteworthy to recognize that lithium's influence on mTOR extends beyond ischemic stroke." (PMID 38169754, 2024). "Western blot assays shown that the pro-neurite outgrowth effect of ZGP on ischemic stroke may be relate to PTEN/mTOR signal pathway." (PMID 37426810, 2023). "Western blot assays shown that the pro-neurite outgrowth effect of Zuogui Pill on ischemic stroke may be relate to PTEN/mTOR signal pathway." (PMID 37426810, 2023). "We tested whether EA stimulation of the Zusanli (ST36) and Neiguan (PC6) acupoints activates neuroplasticity in rats with ischemic stroke and whether this involves the regulation of axonal regeneration through the mTOR pathway." (PMID 36440366, 2022). "Transcriptomic analysis revealed that mammalian target of rapamycin (mTOR), oxidative phosphorylation, growth factor signaling, and calpain proteases signaling pathways were generally up-regulated in circulating neutrophils of ischemic stroke patients." (PMID 34248961, 2021). "Furthermore, transfection with miR-155 decreases the expression of Rheb and mTOR, whereas inhibition of miR-155 plays a protective role in rats with ischemic stroke via phosphorylation of S6K through the Rheb/mTOR pathway." (PMID 33868799, 2021).
ischemic stroke (continued). "Moreover, several studies on the restorative effect of stem cells on the PI3K/Akt/mTOR pathway in ischemic stroke models with positive results have been reported." (PMID 34815829, 2021). "Activating mTOR may limit neuronal death and improve neurological outcomes following ischemic stroke." (PMID 34226528, 2021). "Also, the mechanism of EA treatment exerted neuroprotection after ischemic stroke by regulating the PI3K/AKT/mTOR pathway." (PMID 32477073, 2020). "In the present study, we investigated whether the neuroprotective effects of FTY720, following ischemic stroke, are accompanied by the regulation of autophagic activity, and the putative role of the mTOR pathway in this process." (PMID 29186197, 2017). "Therefore, this study assesses the effects of rapamycin on mTOR signaling and neuronal survival in an in vitro model of ischemic stroke, OGD." (PMID 23861877, 2013). "In the context of ischemic stroke, peripheral blood-derived exosomes containing hyaluronan-binding protein 2 (HABP2) promote the expression of protease-activated receptors 1 (PAR1) in astrocytes causing activation of the phosphoinositide 3-kinase (PI3K) / AKT / mTOR pathway." (PMID 39652154, 2024). "Therefore, we hypothesized that EA may promote axonal regeneration after ischemic stroke and exert neuroprotective effects by activating the mTOR pathway." (PMID 36440366, 2022). "Analysis of the expression of key genes of the PI3K/Akt/mTOR and PI3K/Akt/FOXO3a signaling pathways in the cerebral cortex revealed pronounced age-related differences in their activation following ischemic stroke." (PMID 41515961, 2025). "Higher levels of MEG3 in ischemic stroke lead to the upregulation of GRB2 by binding to and inhibiting miR-378, resulting in the destruction of the Akt/mTOR pathway." (PMID 39021183, 2024). "Another molecule that is upregulated in astrocytes and neurons during ischemic strokes is SerpinA3N, which induces increased phosphorylation of AKT and mTOR in vitro and in vivo." (PMID 39652154, 2024). "The search strategy employed a combination of keywords and phrases related to ischemic stroke, molecular mechanisms, pharmacological treatments, RhoA/ROCK, mTOR pathways, MSCs, EVs, and secretome." (PMID 38666949, 2024). "In ischemic stroke, the NLRP3-related protein expression that mitigates autophagy activation includes AMPK, mTOR, and ULK1." (PMID 37915409, 2023). "The elevation of p-Akt/p-mTOR and the reduction of IL-1β, TLR4, p-38, and p-p38 levels have also been observed after curcumin administration in ischemic stroke and were concomitant with curtailed LC-3-II and NLRP3 markers." (PMID 37915409, 2023). "In conclusion, we demonstrated that elevated P-gp levels following ischemic stroke exacerbated BBB breakdown and brain inflammatory response by increasing Akt/mTOR activity and suppressing autophagy activation." (PMID 36186136, 2022). "The results of this study suggest that 25-HC inhibits autophagy dysfunction via the mTOR/STING pathway, thereby alleviating MCAO-induced ischemic stroke." (PMID 34406977, 2021). "We aimed to define age-dependent features of neuronal metabolism and cell death after ischemic stroke by assessing NeuN, NSE, and Caspase-3 in human cortical neurons and by comparing transcriptional activity within PI3K/Akt/mTOR and PI3K/Akt/FOXO3a pathways across age groups." (PMID 41515961, 2025). "In summary, this study reveals that lncRNA C2dat2 facilitates autophagy and apoptosis via the miR-30d-5p/DDIT4/mTOR axis in CIRI, improving the understanding of the regulatory mechanism of C2dat2 in CIRI and indicating the potential therapeutic target for ischemic stroke treatment." (PMID 33833132, 2021).
ischemic stroke (continued). "Here, we aimed to evaluate whether EA treatment at the acupoints of Zusanli (ST36) and Quchi (LI11) exerted a neuroprotective effect on ischemic stroke rats by modulating autophagy and apoptosis via the PI3K/AKT/mTOR signaling pathway." (PMID 32477073, 2020). "Previous studies have also highlighted the protective effects of EA following ischemic stroke, such as modulating microglial polarization, suppressing inflammation, improving motor function through the PI3K/AKT signaling pathway, and regulating the mTOR signaling pathway via motor cortex activation." (PMID 37829255, 2023). "The results indicated that the levels of LC3 II/I ratio and Beclin-1 increased with time, whereas those of P62, p-mTOR/mTOR, and p-P70S6K/P70S6K were reduced in mouse brain after I/R and N2a cells after OGD/R, confirming the existence of autophagy in ischemic stroke." (PMID 33833132, 2021). "In addition, the effects of 25-HC on STING/mTOR pathway-related protein expression, oxidative damage, apoptosis, and inflammation can be reversed by CMA, suggesting that 25-HC inhibits autophagy through the STING/mTOR pathway, thereby alleviating MCAO-induced ischemic stroke." (PMID 34406977, 2021). "Since mTOR/p70S6K signaling pathway is known to play a pivotal role in regulating autophagy activity, we evaluated whether FTY720 might inhibit autophagy by activating mTOR pathway after ischemic stroke." (PMID 29186197, 2017). "Overall, the results of our study indicated that the AMPK/mTOR signaling pathway played an important role in neuroprotection produced by OGD/R-ADEXs in the early stage of ischemic stroke, but we could not completely rule out whether OGD/R-ADEXs regulated other autophagy-related signaling pathways." (PMID 36539418, 2022).
skin cancer (59 papers, 2008 to 2026). "Dysregulation of mTOR signaling is implicated in a wide range of skin conditions, including inflammatory skin diseases and skin cancers." (PMID 40590148, 2025). "Dysregulated mTOR signaling is tightly associated with the development of several hyperproliferative skin disorders, including skin cancer, and inflammatory skin diseases." (PMID 35938153, 2022). "Certain immunosuppressants such as CNI are associated with an increased risk of skin cancer when compared to mammalian target of rapamycin (mTOR) inhibitors." (PMID 34113803, 2019). "Deregulation of the PI3K/Akt/mTOR pathways has been implicated in the pathogenesis of multiple solid human cancers including several skin cancers." (PMID 31370278, 2019). "The Australian and TUMORAPA trials in large part reached a similar conclusion that mTOR inhibitors inhibit skin cancer in high-risk kidney transplant recipients." (PMID 25699174, 2015). "Results from clinical studies suggest also that patients at a high risk for skin cancer receive the greatest benefit when mTOR inhibitors are used early, before multiple lesions have already developed." (PMID 25699174, 2015). "Among all signaling pathways activated by UVB irradiation, phosphoinositide 3-kinase (PI3K)/Akt/mammalian target of rapamycin (mTOR) pathway enhances the survival of mutated cells, thereby promoting skin cancer." (PMID 24365180, 2013). "Additionally, we found that the inhibitory effect of curcumin on skin cancer proliferation was associated with inhibition of AKT/mTOR and ERK signaling." (PMID 23316365, 2012). "α-Mangostin inhibits the formation and growth of skin cancer by inhibiting PI3K/AKT/mTOR signal transduction, inducing tumor autophagy and promoting apoptosis, thus significantly reducing the incidence." (PMID 40375996, 2025). "Panduratin A, apigenin, harmine, sinomenine, curcumin, resveratrol, erufosine, WYE-354, and α-mangostin are some of the natural compounds involved in inducing autophagy in skin cancer by targeting the PI3K/Akt/mTOR pathway." (PMID 39371094, 2024). "In the human cutaneous SCC cell line A431 cells, GL-V9 promotes autophagy and stops the progression of chemically produced primary skin cancer in mice by blocking the Akt/mTOR pathway and triggering autophagy." (PMID 39371094, 2024). "Particularly, our study delineated the involvement of autophagy-related molecular pathways, including the AMPK and mTOR pathways, in the regulation of skin cancer using natural, semisynthetic, and synthetic molecules within the human body." (PMID 39371094, 2024). "The PI3K/AKT/MTOR pathway is associated with skin cancer, perhaps through the involvement of the AKT/MTOR pathway on inhibiting the death of skin cells." (PMID 36611750, 2022). "Collectively, these studies demonstrate that aberrant mTOR signaling activity in skin carcinogenesis and raise inhibiting mTOR signaling as an attractive therapeutic target in skin cancer." (PMID 35938153, 2022). "Activation of the AKT/mTOR pathway is often seen in oral squamous cell carcinoma, skin cancer, and RCC." (PMID 33259779, 2021). "Numerous reports have shown that PI3K/AKT/mTOR/S6K1 pathway can be activated in skin cancers by UV radiation exposure." (PMID 33996865, 2021). "Switching from calcineurin to mTOR inhibition halved skin cancer rates in transplant patients, as mTOR inhibitors can also suppress DNA damage, proliferation and angiogenesis." (PMID 34553848, 2021). "Here we have focused the effects of AKT and related signaling (PI3K/AKT/mTOR) pathways by regulators derived from plants and suggest the need for efficient treatment in skin cancer therapy." (PMID 32962182, 2020). "Skin cancers are partly caused by UVA and UVB exposure, which is also associated with the mTOR pathway deregulation." (PMID 31370278, 2019).